DEFA1 (defensin alpha 1)
Description:
Effector molecule of the innate immune system that acts via antibiotic-like properties against a broad array of infectious agents including bacteria, fungi, and viruses or by promoting the activation and maturation of some APCs. Interacts with the essential precursor of cell wall synthesis lipid II to inhibit bacterial cell wall synthesis. Inhibits adenovirus infection via inhibition of viral disassembly at the vertex region, thereby restricting the release of internal capsid protein pVI, which is required for endosomal membrane penetration during cell entry. In addition, interaction with adenovirus capsid leads to the redirection of viral particles to TLR4 thereby promoting a NLRP3-mediated inflammasome response and interleukin 1-beta (IL-1beta) release. Induces the production of proinflammatory cytokines including type I interferon (IFN) in plasmacytoid dendritic cells (pDCs) by triggering the degradation of NFKBIA and nuclear translocation of IRF1, both of which are required for activation of pDCs.
Synonyms: HP-1; HP1; DEF1; DEFA2; MRS; HNP-1
Tractability: Antibody: its Gene Ontology location is reachable by antibodies, with high confidence; UniProt places it where antibodies can reach, with medium confidence; UniProt predicts a signal peptide or a membrane-spanning region.
Gene: Protein-coding gene on chromosome 8 (6,977,649 to 6,980,092, reverse strand). Ensembl gene ENSG00000206047.
Subcellular location: Secreted
Pathways (Reactome):
Immune System: Alpha-defensins; Defensins; Neutrophil degranulation
Gene Ontology:
Molecular function: pore-forming activity; protein binding
Biological process: antibacterial humoral response; antimicrobial humoral immune response mediated by antimicrobial peptide; defense response to Gram-positive bacterium; estrogen receptor signaling pathway; innate immune response in mucosa; killing of cells of another organism; T cell chemotaxis; chemotaxis; defense response to Gram-negative bacterium; disruption of plasma membrane integrity in another organism; immune response; innate immune response; defense response
Cellular component: extracellular exosome; extracellular region; azurophil granule lumen; Golgi lumen
Homologues: Orthologues: chimpanzee DEFA1 (96% identical), macaque DEFA1B (84% identical), rabbit MCP-1 (44% identical), rat Defa5 (36% identical), mouse Defa2 (35% identical), mouse Defa20 (35% identical), mouse Defa32 (35% identical), mouse Defa33 (35% identical), mouse Defa34 (35% identical), mouse Defa5 (35% identical), rat Np4 (35% identical), mouse Defa17 (34% identical), and 30 more. Paralogues in human: DEFA1B (100% identical), DEFA3 (99% identical), DEFA6 (49% identical), DEFA5 (48% identical), DEFA4 (46% identical).
Diseases named in the same sentence as DEFA1 in open-access papers:
DEFA1 is named in the same sentence as 62 diseases in open-access papers, as found by Europe PMC text mining. Sharing a sentence is not in itself a finding about the gene and the disease. The quoted sentences say what the papers report.
Sepsis (10 papers, 2018 to 2025). Sepsis is defined as life-threatening organ dysfunction caused by a dysregulated host response to infection. "Recently, experimental evidence has highlighted the genetic association between the clinical phenotype of sepsis and DEFA-1/DEFA-3 copy number." (PMID 31877866, 2019). "A genetic association study found that increased copy number of the HNP-encoding gene DEFA1/DEFA3 is a risk factor for organ dysfunction during sepsis development." (PMID 30718392, 2019). "We did not observe similar correlation between outcomes and raw defensin-α1 protein levels in our study cohort; however, changes in the levels of DEFA1 RNA over a 3-hour period was associated with clinical decompensation and emergence of more severe sepsis/septic shock." (PMID 41385588, 2025). "However, despite the implication of HNP1–3 in sepsis outcomes, little is known about the functional role of DEFA1/DEFA3 variants in the pathophysiology of sepsis." (PMID 30718392, 2019). "Thus, combined with our previous case-control genetic association study, these human and transgenic mouse model-based findings indicate that HCN of DEFA1/DEFA3 is a causative genetic factor for sepsis development." (PMID 30718392, 2019). "Interestingly, higher copy numbers of DEFA1/DEFA3 CNV have been associated with a risk for severe sepsis." (PMID 29950924, 2018). "Interestingly, they reported that transgenic mice carrying more copies of the DEFA1/DEFA3 suffer from more severe sepsis and mortality than those with low copy numbers of DEFA1/DEFA3 and wild-type mice, which is caused by broader endothelial barrier dysfunction and EC pyroptosis." (PMID 32948742, 2020). "Examples of genes related to this pathway that were differentially expressed in our sepsis samples include DEFA1, DEFA3, S100A8, S100A9 and RNASE6." (PMID 37731199, 2023). "Using a transgenic mouse model, we further confirmed that mice with high copy numbers of DEFA1/DEFA3 suffer from more severe pathophysiologic changes during sepsis progression." (PMID 35935811, 2022). "In another study, the same group also observed that DEFA1/DEFA3 participate in host immune response to sepsis and its higher copy number variation was significantly associated with sepsis risk." (PMID 35345767, 2022). "A study showed that the overexpression of HNP1-3 (DEFA1/DEFA3) remarkably damaged the clinical characteristics of sepsis, making patients in China displayed a high gene copy number of DEFA1/DEFA3 means more easily affected by severe sepsis." (PMID 36776394, 2022). "Human and mouse studies have shown that increased copy numbers of DEFA1/DEFA3 worsen sepsis outcomes." (PMID 35935811, 2022). "To determine how the increased dose of DEFA1/DEFA3 led to endothelial cell pyroptosis during sepsis, we first examined the protein level of HNP1–3 in vivo after septic challenge." (PMID 30718392, 2019). "Here, we present experimental evidence for the impact of DEFA1/DEFA3 CNVs on sepsis development and explore the mechanism by which HNP1–3 promotes endothelial barrier dysfunction and endothelial cell pyroptosis." (PMID 30718392, 2019). "Experiments to analyze the specific roles of DEFA1/DEFA3 CNVs in sepsis are challenging because mice naturally lack neutrophil defensins." (PMID 30718392, 2019). "To test the effect of increased dosage of DEFA1/DEFA3 genes in another clinically relevant murine model of sepsis, we used intraperitoneal administration of Escherichia coli." (PMID 30718392, 2019). "Taken together, these data show that endothelial barrier dysfunction contributes to sepsis deterioration in mice carrying HCN of DEFA1/DEFA3 genes." (PMID 30718392, 2019). "We thus demonstrate that DEFA1/DEFA3 copy number variation strongly modulates sepsis development in vivo and explore a paradigm for the precision treatment of sepsis tailored by individual genetic information." (PMID 30718392, 2019).
Sepsis (continued). "To investigate the potential role of genetic CNVs of DEFA1/DEFA3 in sepsis development in vivo, we constructed a transgenic mouse model that expresses human DEFA1/DEFA3 under its endogenous regulatory sequences to recapitulate human defensin pathophysiology." (PMID 30718392, 2019). "Our previous genetic association study found that DEFA1/DEFA3 (the genes that encode HNP1-3) copy number variations are genetic risk factors for sepsis, and that individuals with high copy numbers of DEFA1/DEFA3 are more susceptible to sepsis." (PMID 35935811, 2022). "We asked whether endothelial dysfunction played an important role in worse sepsis outcomes of mice with HCN of DEFA1/DEFA3 genes." (PMID 30718392, 2019). "Thus, using the DEFA1/DEFA3 transgenic mouse models, these findings suggest a causative link between DEFA1/DEFA3 CNVs and sepsis outcome." (PMID 30718392, 2019). "Notably, at 72 h after sepsis development, the mice carrying HCN of DEFA1/DEFA3 showed a marked loss of CD31+ endothelial cells in microvessels from lung, kidney, and mesentery, which presumably resulted from lethal injury of the endothelial cells." (PMID 30718392, 2019). "Transgenic mice models were engineered to produce a high gene copy number of DEFA-1/DEFA-3, which manipulated the outcome of sepsis progression." (PMID 31877866, 2019). "Taken together, these findings demonstrate that after sepsis onset, vascular endothelia are excessively activated and dysfunctional in mice carrying HCN of DEFA1/DEFA3." (PMID 30718392, 2019). "In the present study, mice engineered to have HCN of DEFA1/DEFA3 genes showed more severe organ damage and a worse outcome after sepsis challenge, indicating a genotype-restricted function in phenotype development." (PMID 30718392, 2019). "To examine the therapeutic potential of the blocking antibody in established sepsis, we treated mice with HCN of DEFA1/DEFA3 at an initial time of 12 h post-CLP and thereafter at 36 and 60 h." (PMID 30718392, 2019). "In both assays, compared with WT mice and the mice with LCN, those carrying HCN of DEFA1/DEFA3 had significantly increased extravasation of dyes in the vessel beds of lungs, kidneys, and mesentery at 72 h after the initiation of sepsis." (PMID 30718392, 2019). "To confirm the contribution of cell-specific expression of the transgenes to the observed effect on sepsis, we generated BM-chimeric mice by reconstituting lethally irradiated WT mice with syngeneic BM with LCN of DEFA1/DEFA3, HCN of DEFA1/DEFA3, or WT." (PMID 30718392, 2019). "In fact, DEFA1 RNA levels were similar between more severe forms of sepsis (Sepsis/Shock), sepsis, and non-ED patient controls with self-reported infections." (PMID 41385588, 2025). "In DEFA1/DEFA3 transgenic mice, increased gene copy numbers of DEFA1/DEFA3 worsen sepsis by inducing endothelial pyroptosis and vascular permeability in a canonical Nod-like receptor family pyrin domain containing 3 (NLRP3)/caspase-1 inflammasome dependent manner." (PMID 35935811, 2022). "In this study, the protein levels of vascular cell adhesion molecule 1 (VCAM1) and intercellular adhesion molecule 1 (ICAM1) in the lung tissue of DEFA1/DEFA3-HCN mice were significantly higher than those of DEFA1/DEFA3-LCN mice and WT mice 24 hours after the onset of disease septicemia." (PMID 36776394, 2022). "These dose-dependent effects of HNP-1 on endothelial cell viability were closely consistent with in vivo findings showing that mice carrying HCN of DEFA1/DEFA3 had more pyroptotic endothelial cells than those with LCN of DEFA1/DEFA3 and WT controls during sepsis development." (PMID 30718392, 2019). "However, few downregulated proteins in sepsis patients compared to HC were AHSG, and PROS1, whereas compared to w/o sepsis, patients were AHSG, PROS1, DEFA1, SERPINA3, MPO, and MMRN1 (Azurophil granule, azurophil granule lumen and secretory granule lumen (GO:0042582, GO:0035578 and GO:0034774))." (PMID 35681439, 2022).
Sepsis (continued). "We subjected mice carrying the HCN of DEFA1/DEFA3 genes to the CLP model and treated them three times with the blocking antibody (300 μg, by tail vein injection; immediately, 24 and 48 h after performance of sepsis), or administered an equal amount of mouse IgG or an equal volume of normal saline." (PMID 30718392, 2019). "Thus, we employed transgenic mice expressing HNP1–3 to explore the nonredundant functions of DEFA1/DEFA3 genes in sepsis." (PMID 30718392, 2019). "Therefore, we questioned whether increased DEFA1/DEFA3 gene dosage could affect the host inflammatory response and bacterial clearance during sepsis." (PMID 30718392, 2019). "However, depletion of macrophage/monocytes did not confer any protection against lethal sepsis for mice carrying HCN of DEFA1/DEFA3." (PMID 30718392, 2019).
COVID-19 (9 papers, 2021 to 2025). A disease caused by infection with severe acute respiratory syndrome coronavirus 2. "Recently some studies indicate that elevated Levels of Alpha-Defensins (DEFA1) is associated with disease severity in COVID-19 and can inhibit SARS-CoV-2 infection." (PMID 38115996, 2023). "The severity of COVID-19 is associated with significant changes in the activation of neutrophil-related transcripts, such as DEFA1, and decreased levels of T cell-related transcripts, such as the T cell receptor." (PMID 35081105, 2022). "The observations of raised levels of these proteins much before the appearance of secondary infection provide important evidence for the association of higher expression levels of DEFA1/Calprotectin/MPO levels with COVID-19 severity." (PMID 34746027, 2021). "Association of raised DEFA1 and calprotectin with poor clinical outcome raises possibility of crucial roles of these molecules in the COVID-19 pathogenesis." (PMID 34746027, 2021). "Higher DEFA1–3 expression reduced COVID-19 risk by 81.6% (OR = 0.184, p = 0.012)." (PMID 40904798, 2025). "Consequently, DEFA1–3 expression may serve as a valuable biomarker for assessing susceptibility to COVID-19." (PMID 40904798, 2025). "In summary, our findings demonstrate that the protective effects of vitamin D in COVID-19 are more closely associated with local VDR expression and innate antimicrobial pathways, particularly DEFA1-3, than with systemic 25(OH)D concentrations alone." (PMID 40904798, 2025). "This prospective observational study aimed to assess how serum 25(OH)D concentrations and nasopharyngeal expression of VDR, DEFA1-3, and CCL20 are associated with COVID-19 status in Lebanese participants tested between January and March 2024." (PMID 40904798, 2025). "This study aimed to determine how serum vitamin D status and gene expression of VDR, DEFA1-3, and CCL20 associate with COVID-19 risk in a Lebanese cohort." (PMID 40904798, 2025). "Very recently, increased serum DEFA1 levels were reported in COVID-19 patients suffering from acute respiratory distress syndrome." (PMID 34746027, 2021). "The AUC value for alpha-defensin was 0.78 ± 0.06 (95% CI = 0.66 to 0.89, p<0.0002), suggesting that DEFA1 levels could act as a potential biomarker in predicting disease severity in COVID-19." (PMID 34746027, 2021). "DEFA1 and S100A8/A9 expression levels were significantly higher in patients with fatal outcome (p=0.004; p=0.03 respectively) suggesting that neutrophil activation is associated with mortality in COVID-19 patients." (PMID 34746027, 2021). "In the COVID-19 positive group, VDR expression showed a significant positive correlation with DEFA1-3 (r = 0.45, p < 0.05)." (PMID 40904798, 2025). "The gene expression comparison according to the COVID-19 disease status showed that the normalized VDR, DEFA1–3 and CCL20 expression is significantly higher in the negative group than in the positive group (P<0.05)." (PMID 40904798, 2025). "In a subset of 70 individuals stratified by COVID-19 status, we measured VDR, DEFA1-3, CCL20, and GAPDH expression by RT-qPCR." (PMID 40904798, 2025). "In this study, we have observed significantly elevated levels of α-defensins (DEFA1 and DEFA3) in COVID-19 and GBS." (PMID 38115996, 2023). "Several enzymes with antimicrobial activity are increased in COVID-19 patients’ sera, including CST3, DEFA1, and LYZC, indicating a possible secondary bacterial infection [TE97]." (PMID 34876157, 2021). "This study provides comparative, circulatory expression profiles of DEFA1, S100A8/A9 and MPO in COVID-19 patients with different clinical presentations." (PMID 34746027, 2021). "Their protective role was further supported by our finding of higher DEFA1–3 expression in COVID-19-negative individuals, consistent with reduced viral susceptibility." (PMID 40904798, 2025).
COVID-19 (continued). "The COVID-19 neutrophils likewise exhibited >5-fold elevated neutrophil elastase activity on a per-cell basis, consistent with the elevated transcript levels of cathepsin G (CTSG) and DEFA1, and the de-compacted, DAPIbright chromatin." (PMID 35081105, 2022).
viral infection (5 papers, 2014 to 2025). "Our observation is supported by the fact that the main producers of DEFA1 and other antimicrobial molecules are short-lived neutrophils, the first immune cells to travel to the sites of bacterial, fungal, and viral infections." (PMID 28637910, 2017). "They identified blood DEFA1 RNA levels and neutrophil elastase activity—key components of neutrophil extracellular traps (NETs)—as potential biomarkers reflecting host immune responses following viral infection." (PMID 39857114, 2025).
hyperlipidemia (3 papers, 2016 to 2022). "We recently reported that the PPBP and DEFA1/DEFA3 genes may be feasible synergistic biomarkers for CHD risk in Thai men with hyperlipidemia." (PMID 35734636, 2022). "We recently reported that the PPBP and DEFA1/DEFA3 genes could act as biomarkers for CHD risk in Thai men with hyperlipidemia." (PMID 35734636, 2022). "The present study aimed to determine the values of the PPBP and DEFA1/DEFA3 genes and their encoded proteins as biomarkers of CHD risk in postmenopausal Thai women with hyperlipidemia." (PMID 35734636, 2022). "Based on these data, we suggest that significantly increased expression of both PPBP and DEFA1/DEFA3 and their encoded proteins has the potential to be established as a synergistic predictive biomarker for CHD risk in hyperlipidaemia patients." (PMID 28420383, 2017). "Our results showed that DEFA1/DEFA3 mRNA expression was not significantly different between these groups (p > 0.05), i.e., DEFA1/DEFA3 expression was similar between hyperlipidemia and CHD patients." (PMID 27430968, 2016). "DNA microarray analysis revealed that DEFA1/DEFA3 are expressed in both hyperlipidemia and CHD patients." (PMID 27430968, 2016). "PPBP and DEFA1/DEFA3 could be potential CHD biomarkers in Thai hyperlipidaemia patients." (PMID 28420383, 2017). "Among eight potential markers, PPBB and DEFA1/DEFA3 were the most strongly correlated with CHD development, and show promise for further application as inflammatory markers to synergistically predict the risk of CHD development in Thai hyperlipidaemia patients." (PMID 28420383, 2017). "Therefore, we suggest that DEFA1/DEFA3 may serve as a biomarker for CHD development in hyperlipidemia patients." (PMID 27430968, 2016). "The results indicate that gene and protein expression levels of PPBP, but not DEFA1/DEFA3, and HNP-1–3, may be feasible biomarkers for assessing CHD risk in postmenopausal Thai women with hyperlipidemia." (PMID 35734636, 2022).
Obesity (3 papers, 2011 to 2024). Accumulation of substantial excess body fat. "Many of the upregulated immature neutrophil genes (e.g., OLFM4, DEFA1, ELANE, CEACAM6, CEACAM8, CTSG) have been found to be differentially expressed in persons with obesity and type 2 diabetes, both common comorbidities with psychotic disorders." (PMID 37147304, 2023).
type 2 diabetes (3 papers, 2011 to 2025). "This study provides new data on the relationship between the levels of DEFA1, progranulin, and NRG4 and the presence of autonomic neuropathy in patients with type 2 diabetes." (PMID 40137134, 2025).
coronary heart disease (2 papers, 2017 to 2020). "Recently, DEFA1 expression levels have been reported to be associated with coronary heart disease (CHD) in hyperlipidemic patients." (PMID 31935243, 2020).
Hospital-Acquired Infections (2 papers, 2018 to 2023). "It was also reported that lower copy numbers of the DEFA1 gene contribute to a higher risk for hospital-acquired infections." (PMID 36980071, 2023).
rheumatoid arthritis (2 papers, 2007 to 2015). A chronic, systemic autoimmune disorder characterized by inflammation in the synovial membranes and articular surfaces. "It is reported that up-regulation of human DEFA1 mRNA in bone marrow-derived mononuclear cells is associated with rheumatoid arthritis in human." (PMID 26252209, 2015). "On the other hand, DEFA3 but not DEFA1, has been found upregulated in patients with systemic lupus erythematosus, idiopathic thrombocytopenic purpura or rheumatoid arthritis, suggesting that DEFA3 upregulation might be a general feature of autoimmune diseases." (PMID 17214878, 2007).